RN7SL689P (RNA, 7SL, cytoplasmic 689, pseudogene)
Gene: Miscellaneous RNA gene on chromosome 5 (123,022,487 to 123,022,783, reverse strand). Ensembl gene ENSG00000263432.
Homologues: Orthologues: chimpanzee Metazoa_SRP (98% identical), macaque Metazoa_SRP (92% identical), guinea pig Metazoa_SRP (60% identical). Paralogues in human: RN7SL2 (82% identical), RN7SL1 (82% identical), RN7SL296P (81% identical), RN7SL126P (80% identical), RN7SL3 (80% identical), RN7SL357P (80% identical), RN7SL255P (80% identical), RN7SL45P (80% identical), RN7SL478P (79% identical), RN7SL516P (79% identical), RN7SL122P (79% identical), RN7SL322P (79% identical), and 703 more.